SNORA48B (small nucleolar RNA, H/ACA box 48B)
Gene: Small nucleolar RNA gene on chromosome X (3,532,117 to 3,532,251, reverse strand). Ensembl gene ENSG00000212214.
Gene Ontology:
Biological process: RNA processing
Cellular component: nucleolus
Homologues: Orthologues: chimpanzee SNORA48B (100% identical). Paralogues in human: SNORA48 (92% identical).